INS (insulin)
Diseases named in the same sentence as INS in open-access papers (continued):
Sharing a sentence is not in itself a finding about the gene and the disease.
melanoma (continued). "In this study, we determined the metabolic profile of normal human immortal keratinocyte cells (HaCaT) and human melanoma cells (SK-MEL-28, SK-MEL-5, and RPMI-7951) by their ability to uptake glucose induced by insulin or excrete lactate and glutamate." (PMID 37569428, 2023). "Due to the initial spread of melanoma cells after intraperitoneal injection, it is likely that irreversible structural damage of pancreatic tissue has occurred, which may explain a persistent reduction of plasma insulin levels and subsequent lower AKT activation in the heart." (PMID 34669013, 2021). "In summary, we have identified and validated a serum-free and insulin supplemented (ITS) medium condition that is well suited for controlled study of lipogenic gene activation and its mechanism of action in melanomas, and perhaps other cancer cell types." (PMID 30970006, 2019). "To evaluate the roles DNFA in cell proliferation and survival, we cultured melanoma cells in the lipid-free 1% ITS medium, using insulin as a growth factor to stimulate proliferation." (PMID 31316083, 2019). "GPR174 is strongly expressed in melanoma cells, and although insulin increased GPR174 expression, it did not play a role in regulating cell proliferation." (PMID 37761999, 2023). "Insulin supplementation has been demonstrated to slow tumour progression in mice carrying B16F10 melanoma, suggesting that reduced tumour growth seen in our SIRT6 over‐expressing mice could be attributed partly to upregulation of insulin levels in these mice." (PMID 34212132, 2021). "We report here that a serum-free and insulin-supplemented culture medium condition, 1% ITS supplemented RPMI-1640, supports DNFA and DNCS pathway activation as well as proliferation and survival of human melanoma cell lines." (PMID 30970006, 2019). "We did not detect any endogenous insulin or IGF2 RNA or protein levels in any of the four melanoma cells tested, but our RT-qPCR studies revealed presence of IGF1 RNA that is supported by recent reports." (PMID 28223541, 2017). "Here we report that a defined serum free cell culture medium condition containing insulin, transferrin and selenium (ITS) supports controlled study of transcriptional regulation of de novo fatty acid (DNFA) production and de novo cholesterol synthesis (DNCS) in melanoma cell lines." (PMID 30970006, 2019). "We detected no IGF2 or insulin RNA expression in the melanoma cell lines." (PMID 28223541, 2017). "However, the role of endocrine or paracrine IGF1, insulin or IGF2 in an entire organism might reveal additional effects and provide for a holistic analysis of this aspect of IGF regulation in melanoma." (PMID 28223541, 2017).
-deficient (54 papers, 2010 to 2025). "A deeper understanding of insulin’s role in proteostasis is crucial for both normal physiology and pathological conditions like T1D, where insulin deficiency disrupts protein metabolism." (PMID 40725728, 2025). "Although we were excited by this unprecedented finding, it was incompatible with the prevailing view that DKA is purely a consequence of insulin deficiency in the periphery." (PMID 40759579, 2025). "LADA patients have slow progressive β-Cell destruction, which eventually leads to insulin deficiencies and, therefore, the requirement for insulin therapy." (PMID 35804315, 2022). "It is also likely that some of the effects of loss of E2 on insulin action are due to the increased adiposity associated with E2-deficiency." (PMID 25883987, 2015). "Interestingly, higher circulating concentrations of 2-HB are associated with perturbation in biotin metabolism, specifically in inherited biotinidase deficiencies, and poor biotin status has been associated with insulin resistant states (and references therein)." (PMID 21170321, 2010). "There is a four-fold increase in β cell proliferation in young mice after the administration of streptozotocin (STZ), a chemical that is toxic to the β cells in mammals and normally is used for inducing insulin secretion deficiency models in rodents, whereas no changes are observed in older mice." (PMID 22675349, 2012).
cardiomyopathy (54 papers, 2008 to 2025). A disease of the heart muscle or myocardium proper. "Individual risks factors including cardiomyopathy, active-smoker and insulin use were potential risk factors for mortality." (PMID 35637232, 2022). "Susceptibility of heart SSM and IFM to cardiomyopathy has been shown to be different in obese and insulin resistant animal models." (PMID 32214195, 2020). "Therefore, disruption or disturbance of different nodes within this regulatory circuit may impair cellular Ca2+ handling and cause cardiac insulin resistance, which eventually leads to the development of cardiomyopathy." (PMID 39872684, 2022). "Thus, the underlying mechanism for the blood glucose lowering effect of MPT0E014 in DM cardiomyopathy may be caused by improving insulin sensitivity that was attributed to an amelioration of inflammation." (PMID 27446205, 2016). "Increased plasma BCAA concentrations have been found in obese and type 2 DM patients, and DM-induced rodents with cardiomyopathy, and have been suggested to impair insulin-stimulated glucose uptake via the mTORC1 pathway." (PMID 40759793, 2025). "After adjusting for potential confounders, the risk factors of inhospital mortality were HAP (AHR 1.75; 95% CI 1.01–3.03) compared with CAP, higher age, cardiomyopathy, history of insulin, active smoking, qSOFA ≥ 2 and serum HCO3 ≤ 15 mEq/L." (PMID 35637232, 2022). "Individual risks factors including cardiomyopathy, active-smoker and insulin use posed potential risks for mortality." (PMID 35637232, 2022). "It has been suggested that cardiomyopathy is an insulin resistance state and this limits cardiac metabolic efficiency." (PMID 34778146, 2021). "Regarding the novel miRNAs of M. koenigii, mko-miRN6-5p targeted the highest number of human genes, followed by mko-miRN3-3p and mko-miRN2-3p, which are related to insulin secretion, cardiomyopathy, and autoimmune thyroid disease pathways, respectively." (PMID 35009050, 2021). "The major signaling pathways involved include cardiomyopathy, insulin secret, cardiac muscle contract, calcium signaling pathway, Wnt signaling pathway, PI3K-Akt signaling pathway and cardiology pathway, which directly regulated muscle development." (PMID 34938736, 2021). "Activation of the insulin/IGF-1 signaling cascade is markedly inhibited in the hearts of wild-type mice following induction of cardiomyopathy." (PMID 21084725, 2010). "We also considered disease-gene network annotations and found that DEGs and DSGs in CMs are both enriched for genes linked to cardiovascular diseases, including different forms of cardiomyopathies and vascular disorders across all treatments except insulin for DSGs." (PMID 33988505, 2021). "Although these results are convincing, one caveat is that 11β-HSD1 inhibition improves insulin sensitivity which may mask the direct beneficial effects of 11β-HSD1 inhibition of cardiomyopathy." (PMID 29221204, 2017). "Interestingly, the pathway analysis of the genes expressed in hearts of MR mice showed an upregulation of adipocytokines and insulin signaling, whereas cardiomyopathy pathways were downregulated." (PMID 25744495, 2015). "When compared with a previous study using microarrays of animals of BC1_LD population, the insulin and the calcium signalling, the regulation of the cytoskeleton, the focal adhesion dynamics, the leukocyte accumulation and cardiomyopathies-related pathways were found in common." (PMID 24926690, 2014). "Moreover, we here show that activation of mitochondrial metabolism is able to sustain activation of the Akt/PKB survival pathway through the insulin/IGF-1 receptor signaling axis under conditions of ROS-induced cardiomyopathy." (PMID 21084725, 2010). "In males, only six pathways were found to be in common to all three models (apelin signaling, insulin signaling, focal adhesion, Huntington disease, oxytocin signaling and thermogenesis), none of which is directly related to cardiomyopathy or ISRmt." (PMID 37691621, 2023).
cardiomyopathy (continued). "Thus, we assumed that insulin treatment after development of adverse cardiac remodeling would display little cardiac protection, if any, against disrupted metabolic pathways preceding T1DM cardiomyopathy." (PMID 35163316, 2022). "Foz mice with MASH, but not insulin resistant WT mice fed the similar HFD diet, show enlarged cardiomyocytes and a cardiomyopathy phenotype with circumferential LV hypertrophy." (PMID 39206703, 2024).
Congenital hyperinsulinism (54 papers, 2008 to 2026). "HH can be transient due to various risk factors, or it can be permanent and inherited due to mutations in key genes involved in insulin secretion, such as congenital hyperinsulinism (CHI)." (PMID 38212772, 2024). "Hypoketotic hypoglycaemia with suppressed plasma fatty acids and detectable insulin suggests congenital hyperinsulinism (CHI), the most frequent cause of persistent neonatal hypoglycaemia." (PMID 37974153, 2023). "Congenital hyperinsulinism (CHI) causes persistent hypoglycemia due to uncontrolled insulin secretion in newborns and infants." (PMID 36339418, 2022). "Congenital hyperinsulinism (CHI) is a heterogenous disease caused by insulin secretion regulatory defects, being ABCC8/KCNJ11 the most commonly affected genes." (PMID 30462810, 2018). "Genetic forms of HH congenital hyperinsulinism (CHI) are due to mutation in the genes involved in the regulation of insulin secretion." (PMID 29280746, 2017). "Conversely, mutations that reduce channel activity cause congenital hyperinsulinism (CHI) characterized by excess insulin release even during hypoglycemia." (PMID 25926814, 2015). "In pancreatic β-cells, KATP channels play a key role in glucose-stimulated insulin secretion, and gain or loss of channel function results in neonatal diabetes or congenital hyperinsulinism, respectively." (PMID 24399968, 2013). "Congenital hyperinsulinism (CHI) is a severe inherited neonatal disorder characterized by inappropriate insulin secretion caused by genetic defects of the pancreatic beta cells." (PMID 35250887, 2022). "Congenital hyperinsulinism (CHI) is a rare yet notable condition that causes persistent and severe hypoglycemia in neonates and infants due to excessive insulin secretion." (PMID 40704143, 2025). "Mutations in this channel can lead to congenital hyperinsulinism (CHI), a disease associated with excessive or unregulated insulin secretion." (PMID 41132793, 2025). "Congenital hyperinsulinism (CHI) is a clinically, genetically and histologically heterogeneous condition caused by inappropriate insulin secretion during hypoglycemia." (PMID 39741883, 2024). "Persistent hyperinsulinemic hypoglycemia of infancy (PHHI) is a life-threatening condition resulting from inappropriately high levels of insulin secretion." (PMID 37013583, 2023). "Hypoketotic hypoglycaemia with suppressed plasma fatty acids and detectable insulin suggests congenital hyperinsulinism (CHI)." (PMID 37974153, 2023). "Congenital hyperinsulinism (CHI), a rare genetic disorder related to mutations in sulfonylurea receptor 1 (SUR1), encoded by ABCC8, is characterized by excessive insulin secretion and hypoglycemia." (PMID 33751396, 2022). "A cluster of genes, whose mutations lead to congenital hyperinsulinism (CHI) in human, are responsible for the regulation of insulin secretion under basal condition." (PMID 33980820, 2021). "Congenital Hyperinsulinism (CHI) is a rare disorder characterized by inappropriately increased insulin secretion from pancreatic beta cells." (PMID 33424766, 2020). "Congenital hyperinsulinism (CHI) presents in the neonatal period or early infancy and is associated with profound hypoglycaemia due to high levels of unregulated insulin secretion." (PMID 31525223, 2019). "Congenital hyperinsulinism (CHI) is characterized by inappropriate insulin secretion despite hypoglycemia." (PMID 29217498, 2018). "For such reasons, 18F-Fluoro-L-DOPA PET has found its role in assessing the altered AADC activity in pancreatic β-cell from increased insulin synthesis and hypersecretion of insulin by these cells in patients with congenital hyperinsulinism (CHI)." (PMID 29117181, 2017). "The focal form of congenital hyperinsulinism (CHI) is characterized by a cluster of abnormal insulin-oversecreting β cells within a restricted area of the pancreas." (PMID 26379717, 2015).
Congenital hyperinsulinism (continued). "Congenital hyperinsulinism is a group of genetic disorders comprising abnormalities in key genes involved in regulating insulin secretion." (PMID 23032149, 2012). "Congenital hyperinsulinism (HI) is an inappropriate insulin secretion by the pancreatic β-cells secondary to various genetic disorders." (PMID 21967988, 2011). "Congenital hyperinsulinism (CHI, OMIM 256450) is a rare genetic disorder characterised by hyperinsulinemic hypoglycemia caused by unpredictable excessive insulin secretion." (PMID 19065272, 2008). "GDH-HI (hyperinsulinism hyperammonemia syndrome; HI/HA syndrome) caused by GLUD1-activating mutations is the second most common cause of congenital hyperinsulinism (CHI MIM256450), which is a genetic and phenotypic heterogeneous group of disorders associated with dysregulated insulin secretion." (PMID 30306091, 2018). "Congenital hyperinsulinism (CHI) comprises a heterogeneous group of genetic disorders with the common finding of recurrent episodes of hyperinsulinemic hypoglycemia due to an inappropriate secretion of insulin by the pancreatic β-cells." (PMID 26316440, 2015). "Studies have demonstrated that congenital hyperinsulinism of infancy (CHI), a rare disease characterized by persistent insulin secretion even under severe hypoglycemia, is frequently caused by trafficking mutations in KATP channel genes." (PMID 24399968, 2013). "Apart from diabetes, the GLP-1R is also an auspicious structural target for the detection of insulinomas and congenital hyperinsulinism (CHI), which are both conditions of hyper-insulin production resulting in hypoglycaemia." (PMID 37665477, 2023). "Congenital hyperinsulinism (CHI), characterized by inappropriate insulin secretion from the pancreatic beta cells, is the most common cause of persistent childhood hypoglycemia." (PMID 35250887, 2022). "Congenital hyperinsulinism (CHI) is a heterogeneous and complex biochemical disorder which is characterized by the dysregulated release of insulin from pancreatic β-cell." (PMID 30873120, 2019). "Congenital hyperinsulinism (CHI) is a heterogenous and complex disorder in which the unregulated insulin secretion from pancreatic beta-cells leads to hyperinsulinaemic hypoglycaemia." (PMID 30873120, 2019). "Congenital hyperinsulinism (CHI) is a rare, heterogeneous disease characterized by inappropriate insulin secretion from pancreatic islet β-cells resulting in hypoglycaemia." (PMID 29116340, 2018). "Persistent hyperinsulinemic hypoglycemia of infancy (PHHI) (MIM# 256450), previously known as nesidioblastosis, is a disorder characterized by impaired suppression of pancreatic insulin secretion, resulting in hypoglycemia." (PMID 25871929, 2015).
magnesium deficiency (54 papers, 2011 to 2026). A nutritional condition produced by a deficiency of magnesium in the diet, characterized by anorexia, nausea, vomiting, lethargy, and weakness. "Recent studies have found that iron deficiency induces hepatocyte insulin resistance and adipogenesis through the HIF2α-ATF4 signaling pathway." (PMID 39464186, 2024). "This phenomenon occurs due to iron deficiency intensifying hepatocyte lipogenesis and insulin resistance through HIF2α-ATF4 signaling, while the accumulation of iron engenders excess reactive oxygen species production, thereby exacerbating liver fibrosis." (PMID 37840106, 2023). "Several small studies have demonstrated deteriorations in glucose tolerance, insulin secretion and sensitivity, and glycosylated hemoglobin in subjects with iron deficiency, which improved with iron supplementation." (PMID 38149144, 2023). "It has been shown that magnesium deficiency favours the formation of free radicals and the increase in sympathetic tone thus hindering the activity of insulin." (PMID 34829645, 2021). "It is well recognized that a temporal iron deficiency sensitizes insulin action, but chronic iron deficiency can accelerate the development of cardiovascular diseases." (PMID 32283758, 2020). "PPARG becomes a functional nutritional disease-associated protein because these phenotypes (altered insulin level, high low-density lipoprotein, and abnormal blood pressure) are potential phenotypes for various nutritional diseases." (PMID 29258237, 2017). "The extent to which there are tissue-specific differences in insulin signaling in response to iron deficiency warrants additional investigation." (PMID 23110872, 2012). "Magnesium deficiency is alsolinked to the inflammatory response and oxidative stress, while magnesiumsupplementation, in contrast, improves insulin sensitivity and reduces insulinlevels." (PMID 21541018, 2011). "Iron deficiency partly protected against the increase in plasma insulin induced by feeding a high fat diet." (PMID 21589859, 2011). "Furthermore, magnesium is critical for proper glucose utilization and insulin signaling, and magnesium deficiency can lead to the dysregulation of ATP-sensitive potassium (KATP) channels in pancreatic β-cells, impairing insulin secretion." (PMID 39385789, 2024). "Within the pancreas, iron deficiency in β cells can result in diminished insulin secretion." (PMID 37840106, 2023). "On the other hand, magnesium deficiency may increase oxidative stress and inflammation, and thus decrease insulin sensitivity." (PMID 36572916, 2022). "We tested whether the acute administration of iron for the correction of iron deficiency influenced insulin secretion and the production of reactive oxygen species." (PMID 35706490, 2022). "Magnesium deficiency may impair insulin secretion because of dysfunction of the ATP-sensitive K+ channels, which will disrupt the normal functioning of beta cells." (PMID 34901114, 2021). "In a recent study in mice iron deficiency impaired insulin secretion and caused diabetes." (PMID 33419045, 2021). "In a randomized study on carbohydrate-intolerant patients, iron depletion to near iron deficiency was associated with a decrease in both fasting and glucose-stimulated plasma insulin concentrations in a subgroup of 17 subjects with hyperferritinemia and non-biopsy-proven NAFLD." (PMID 34300354, 2021). "Magnesium deficiency has been shown to affect glycemic control by way of altered cellular glucose transport, reduced pancreatic insulin secretion, and defective post-receptor insulin signaling." (PMID 30987399, 2019). "A review has shown that magnesium deficiency could impair the insulin signal transduction pathway and may affect the interaction between insulin and insulin receptors." (PMID 28749415, 2017). "In humans and in animal models, magnesium deficiency modulates insulin sensitivity, and may be associated with impaired insulin secretion." (PMID 25268773, 2014).